ADPRM (ADP-ribose/CDP-alcohol diphosphatase, manganese dependent)
Description:
Hydrolyzes ADP-ribose, ADP, CDP-glycerol, CDP-choline, CDP-ethanolamine and cyclic ADP-ribose (cADPR), but not other non-reducing ADP-sugars or CDP-glucose. May be involved in immune cell signaling as suggested by the second-messenger role of ADP-ribose, which activates TRPM2 as a mediator of oxidative/nitrosative stress (By similarity).
Synonyms: C17orf48; MDS006; Nbla03831
Tractability: PROTAC: ubiquitination databases record sites on it.
Gene: Protein-coding gene on chromosome 17 (10,697,594 to 10,711,558, forward strand). Ensembl gene ENSG00000170222.
Subcellular location (Human Protein Atlas): Nucleoplasm
Pathways (Reactome):
Metabolism: Phosphate bond hydrolysis by NUDT proteins
Gene Ontology:
Molecular function: ADP-ribose diphosphatase activity; CDP-glycerol diphosphatase activity; 2',3'-cyclic-nucleotide 2'-phosphodiesterase activity; manganese ion binding; ADP phosphatase activity; hydrolase activity
Cellular component: cytosol
Genetic constraint (gnomAD): Loss-of-function variants: 17 observed, 26.59 expected, observed/expected ratio (o/e) 0.64, 90% interval 0.44 to 0.96. The upper end of that interval is the gene's LOEUF score, 0.96, which puts it in group 4 of 6, group 1 being the genes least tolerant of losing a copy. Missense variants: 327 observed, 422.81 expected, observed/expected ratio (o/e) 0.77, 90% interval 0.71 to 0.85. Synonymous variants: 133 observed, 149.63 expected, observed/expected ratio (o/e) 0.89, 90% interval 0.77 to 1.03.
Homologues: Orthologues: macaque ADPRM (96% identical), dog ADPRM (88% identical), rabbit ADPRM (85% identical), mouse Adprm (85% identical), pig ADPRM (75% identical), chimpanzee ADPRM (72% identical), rat Adprm (62% identical), tropical clawed frog adprm (51% identical), zebrafish adprm (49% identical), tropical clawed frog adprm.2 (27% identical).
Diseases named in the same sentence as ADPRM in open-access papers:
ADPRM is named in the same sentence as 1 disease in open-access papers, as found by Europe PMC text mining. Sharing a sentence is not in itself a finding about the gene and the disease. The quoted sentences say what the papers report.
tumor (1 paper, 2019). "Notably, the expression of 4 of these genes (TERT, ADPRM, SON and KRT32) were significantly higher in tumor tissues expressing chimeric transcripts compared to tissues without the fusion transcripts (bottom bar graphs)." (PMID 31429776, 2019).